RNU6-253P (RNA, U6 small nuclear 253, pseudogene)
Gene: Small nuclear RNA gene on chromosome 6 (117,457,734 to 117,457,838, reverse strand). Ensembl gene ENSG00000207461.
Homologues: Orthologues: chimpanzee U6 (98% identical), guinea pig U6 (83% identical), pig U6 (82% identical). Paralogues in human: RNU6-21P (87% identical), RNU6-1 (86% identical), RNU6-144P (86% identical), RNU6-15P (86% identical), RNU6-19P (86% identical), RNU6-2 (86% identical), RNU6-20P (86% identical), RNU6-3P (86% identical), RNU6-4P (86% identical), RNU6-5P (86% identical), RNU6-6P (86% identical), RNU6-9 (86% identical), and 1283 more.